STAT3 (signal transducer and activator of transcription 3)
Diseases named in the same sentence as STAT3 in open-access papers (continued):
Sharing a sentence is not in itself a finding about the gene and the disease.
tumor (continued). "Although a few researchers have suggested a tumor-suppressive role of STAT3, the predominant view is that inappropriate STAT3 activation contributes to tumor development and progression through various cytokines and growth factors." (PMID 32257917, 2019). "It is suggested that the signal transducer and activator of transcription (STAT) family proteins, particularly STAT3, selectively induce and maintain the inflammatory microenvironment, at the initiation as well as during progression of the tumor." (PMID 31388334, 2019). "STAT3 activity promotes expansion and activation of myeloid-derived suppressor cells (MDSCs), which mediate immunosuppression and facilitate tumor progression in the MM bone marrow microenvironment." (PMID 31861597, 2019). "The p-STAT3 activation increases the DNMT3b/OCT4 which confers the tumor early recurrence and poor prognosis of HCC patients." (PMID 31771617, 2019). "Collectively, these results indicated that activation of STAT3 was necessary for S1PR1 in promoting tumor cell proliferation and inhibiting tumor cell apoptosis." (PMID 31438989, 2019). "IL-6 is produced by numerous cell types located within the tumor microenvironment, and it acts directly on tumor cells to mediate STAT3 tyrosine phosphorylation and induce the expression of STAT3 target genes." (PMID 30857539, 2019). "Statistical analysis revealed that the expression of STAT3 signaling molecule is connected with tumor location, histological differentiation, and the presence of distant metastases." (PMID 31234597, 2019). "We furthermore show that TYK2 is activated by an autocrine loop involving IL-10 and IL-22 and that STAT1 and STAT3 are essential mediators of aberrant tumor cell survival through activation of the pro-survival protein MCL1." (PMID 30131584, 2019). "It is important to note that by evaluating the whole tumour surface, we observed a specific localization for Stat3 immunopositivity in cells that surround the necrotic areas, but also in cells located at the tumour invasion front." (PMID 31690341, 2019). "Systemic administration of STAT-3 inhibitors not only inhibited tumour growth, but also resulted in the downregulation of immunosuppressive cytokine expression and induction of functional DCs and CTL responses." (PMID 30717461, 2019). "STAT3 mediates the expression of important regulators of cell cycle and apoptosis but it can also play an important role in tumor-immune cells interaction by impairing effective antitumor immunity." (PMID 31581535, 2019). "Consistent with the proposed orthogonal tumor‐promoting activity of IL11‐dependent gp130/STAT3 signaling, tumors of bazedoxifene‐treated Apc‐mutant mice retain excessive nuclear accumulation of β‐catenin and aberrant WNT pathway activation." (PMID 30885958, 2019). "Previous findings from our and other groups had demonstrated that upstream pharmacological inhibition and stable lentiviral depletion of Stat3 provokes great antitumoral responses in vitro and improves survival of tumor-bearing mice in vivo." (PMID 30857197, 2019). "In a positive feedback loop, STAT3 subsequently transduces signals for all members of the IL-6 and IL-10 families, which leads to chronic amplification of pathways that support tumor growth." (PMID 31842362, 2019). "Conversely, inhibition of the IL-6/JAK/STAT3 pathway reduces tumor cell proliferation and restores sensitivity to AR-targeted drugs." (PMID 31143708, 2019). "Aberrant STAT3 activation can also induce inappropriate expression of genes involved in tumor immune evasion such as PD-L1." (PMID 31861597, 2019).
tumor (continued). "In contrast, deletion of SOCS3 in myeloid cells leads to an increased activation of the STAT3 and to differentiation into Gr-1+CD11b+Ly6G+ MDSCs, enhancing tumor growth." (PMID 31480382, 2019). "STAT3 is considered, along with NF-κB, to be a master regulator for tumor progression, acting by supporting inflammation and angiogenesis." (PMID 30646518, 2019). "Activation of STAT3 in the M2 subset leads to tumor-induced immunosuppression and constitutively activates STAT3 inhibiting the expression of mediators required for immune activation against tumor cells." (PMID 31035454, 2019). "This points to the role of cell extrinsic factors in maintaining constitutive STAT3 signaling, including the tumor microenvironment." (PMID 31684088, 2019). "Intratumoral injections showed that AZD9150 inhibited STAT3 expression yet had little effect on the primary growth of tumor xenografts." (PMID 31803140, 2019). "This can be partly explained by the fact that STAT3 inhibits the ID2 (inhibitor of differentiation 2) expression which promotes tumor immunity." (PMID 31480382, 2019). "These anti-tumor activities arise as a result of disruption in the SHP-1/JAK2/STAT3 signaling pathway." (PMID 31569687, 2019). "STAT3 and STAT5 proteins are essential transcription factors that can act in a mutational context-dependent manner as oncogenes or tumor suppressors." (PMID 30818760, 2019). "For instance, lactate produced by highly glycolytic tumors activates the ERK1/2 and the STAT3 signaling in monocytes, promotes their polarization in pro-tumor M2 TAMs, and favors tumor cell proliferation and migration." (PMID 31117237, 2019). "The results showed that the expression of STAT3 protein in tumor tissues of GG genotype patients was significantly higher than that of GA genotype patients." (PMID 31270251, 2019). "The other way for STAT3 to drive tumor immune escape is to regulate the function of stromal cells and more particularly immune cells." (PMID 31480382, 2019). "Both protein and mRNA expression levels of PD-L1 were potently reduced in STAT3 knockdown tumor cells." (PMID 31511071, 2019). "Previous studies have shown that blockade of STAT3 activation in tumor cells induces apoptosis, inhibits cell proliferation and suppresses angiogenesis." (PMID 30914735, 2019). "Recently, however, novel approaches have been developed to directly inhibit STAT3 in human cancers, in the hope of reducing the survival and proliferation of tumor cells." (PMID 31671769, 2019). "Previous studies confirmed that STAT3 acted directly on the proliferation and apoptosis in tumor cells." (PMID 31438989, 2019). "STAT3 activation in tumor cells leads to increased production of immunosuppressive cytokines, including interleukin-6 (IL-6), IL-10, vascular endothelial growth factor (VEGF), and transforming growth factor-b1 (TGF-β1)." (PMID 31671769, 2019). "We demonstrate that specific targeting of Stat3 using LPP significantly reduces tumor growth and improves overall survival." (PMID 30857197, 2019). "Our data further suggest that the STAT3 signaling pathway is involved in HO-1-regulated tumor growth of HCC." (PMID 30606233, 2019). "As with the genes involved in the JAK/STAT3 pathway, 10 mg/kg ajoene extract significantly suppressed the expression of Smad2, Smad3, and Smad4 compared with the tumor control group (Smad2, p = 0.012; Smad3, p = 0.049; Smad4, p < 0.001)." (PMID 31717643, 2019). "Of the known effectors of NF1-loss associated signaling, p38, STAT3, AKT, mTOR, and TGF-β have been previously linked to heightened tumor aggressiveness." (PMID 30967630, 2019). "STAT3 mRNA was positively correlated with hsa-miR-21-5p in tumor and adjacent normal tissues (r = 0.75, 0.78)." (PMID 31270251, 2019). "The relevance of these finding in sporadic CRC was provided by the reduced tumour xenograft development in nude mice upon pharmacological inhibition of the GP130/JAK/STAT3 pathway." (PMID 31091767, 2019).
tumor (continued). "Blockade of oncogenic and angiogenic kinases or downstream STAT3 can retard primary tumor growth, which provides a rationale for many mainstream clinical therapeutics." (PMID 31735169, 2019). "Cytokines and growth factors produced by tumor cells also commonly lead to STAT3 activation in tumor-infiltrating immune cells." (PMID 31671769, 2019). "Both NF-κB and STAT3 interact to promote tumor growth by inducing activation of pathways related to angiogenesis, hypoxia, chemokines, and immunosuppression." (PMID 31921146, 2019). "Some studies support an NFκB and STAT3 crosstalk required for communication between tumor cells and their microenvironment (reviewed in 86)." (PMID 31602271, 2019). "Aberrant activation of STAT3 promotes tumor cell survival, proliferation, and migration through regulating gene expression in multiple oncogenic pathways." (PMID 31861597, 2019). "Overexpression of STAT3 leads to continued growth of tumor cells and promotes other malignant properties such as tumor angiogenesis." (PMID 30913233, 2019). "Immunohistochemical analysis of extracted tumor tissues demonstrated reduced nuclear staining for Ki-67 and downregulation of phospho-STAT3 as well as strong staining for oxidative stress biomarker 8-OHdG." (PMID 30949204, 2019). "Meanwhile, STAT3 and NF-κB interacted with each other to regulate cell tumor angiogenesis and invasiveness." (PMID 31133028, 2019). "Accumulating evidences shows that activation of the IL-17a/JAK2/STAT3 signalling pathway by growth factors or cytokines plays an active role in tumor growth and progression." (PMID 30616627, 2019). "STAT3 is a transcription factor which controls the expression of different genes involved in tumor progression." (PMID 31126035, 2019). "We examined the potential roles and related molecular mechanisms of IL-6 and STAT3 regarding the communication between tumour cells and ADSCs." (PMID 31196220, 2019). "IL-10 is associated with a deficient anti-tumor immune response, increased TGF-β levels and feed-forward STAT3 signaling in tumor cells, microglia and probably astrocytes." (PMID 31186414, 2019). "Western blotting was performed to verify the expression of phospho-EGFR and phospho-STAT3 in tumor tissues." (PMID 31422383, 2019). "In particular, IL-6 has been proven to activate NF-κB and STAT3 pathways to facilitate a tumour micro-environment." (PMID 30962499, 2019). "Abnormal activation of signal transducer and activator of transcription 3 (STAT3) transcription factor has been observed in many human cancers with roles in tumor initiation, progression, drug resistance, angiogenesis and immunosuppression." (PMID 31361777, 2019). "For example, ETV6 is a negative regulator of transcription 3 (Stat3) transcription factor activity, which has the ability to mediate the inhabitation of the proliferation of tumor cells." (PMID 31405076, 2019). "Collectively, our data suggest that the anti‐tumor mechanism of action of bazedoxifene occurs via inhibition of STAT3 signaling and results in suppressed cell survival and proliferation of Apc‐mutagenized intestinal epithelium." (PMID 30885958, 2019). "In patients, blocking STAT3 signaling in reactive astrocytes reduces experimental brain metastasis from different primary tumor sources, even at advanced stages of colonization." (PMID 31130637, 2019). "PTPRK encodes for receptor-type tyrosine-protein phosphatase κ and is believed to mediate tumor suppressive function by interacting with and inactivating STAT3, as mentioned in the “Pro-proliferative signaling pathways” section." (PMID 30935402, 2019). "Other JAK and Src inhibitors such as AZD1480, WP-1066, desatinib, and saracatinib demonstrate the reduction of STAT3 phosphorylation as well as downstream implications like increased apoptosis and decreased tumor growth." (PMID 31781335, 2019).
tumor (continued). "It was clearly shown that STAT3 inactivation in tumor-specific CD8 T cells increased their potential for tumor elimination after adoptive transfer." (PMID 31766350, 2019). "The STAT3 transcription factor can regulate the different important hallmarks of tumor cells, and thus, targeting it can be a potential strategy for treating TNBC, for which only limited therapeutic options are available." (PMID 31058868, 2019). "STAT3 is often overexpressed in tumor cells and tissue samples and regulates the expression of many oncogenes." (PMID 31175144, 2019). "Altogether, these results of the present study suggested that the anti-angiogenesis effect of YPFS participates in its suppression of tumor growth through the TSLP/STAT3 signaling pathway." (PMID 31885639, 2019). "Several studies have validated that increased activity of STAT3 contributes to tumorigenesis by enhancing tumour growth and invasion." (PMID 31295798, 2019). "Mechanically, MPC1 suppressed tumor progression via interacting with mito-STAT3, disrupting STAT3 distribution and inhibiting cyto-STAT3 activation." (PMID 30770798, 2019). "Levels of hsa-miR-149-5p and hsa-miR-21-5p and expression levels of SP1 and STAT3 proteins in tumor tissues and adjacent normal tissues of TSCC patients were ascertained." (PMID 31270251, 2019). "The inhibition of STAT3 signaling by sunitinib arrested the proliferation and reduced the viability of splenic MDSCs in tumor-bearing mice." (PMID 31129755, 2019). "MSC-derived IL-6 protects tumor cells from doxorubicin-induced apoptosis by activating STAT3 signaling." (PMID 30927928, 2019). "Since the major source of IL‐6 is the tumor stroma, STAT3 signaling represents a signaling pathway that is driven by the stroma during the PDA progression." (PMID 31609088, 2019). "Cytokine secretion from GSCs was shown to activate the immunoregulatory protein B7-H4 in tumor macrophages through STAT3 signaling which further blocks T cell function and contributes to immune escape of tumor cells." (PMID 31698775, 2019). "Due to the previous notion that STAT3 is aberrantly activated in tumor-infiltrating immune cells, STAT3 pathway inhibition has been suggested in immunotherapy combinations." (PMID 31796877, 2019). "Understanding mechanistically how STAT3/5 promote transformation and tumor suppression is important for the eventual design of new treatments." (PMID 31557897, 2019). "They found that high expression of PTPRD suppressed STAT3 phosphorylation in healthy liver tissue but low expression of this protein in HCC resulted in the tumor-specific STAT3 activation." (PMID 31547152, 2019). "In contrast, STAT3 knockdown in Monos reduced IL-10-induced PD-L1 protein expression, and p65 knockdown in tumor cells reduced IL-1a-induced PD-L1 expression." (PMID 31730010, 2019). "Accumulating evidences indicated that JAK2/STAT3 are involved in tumor angiogenesis, particularly in the regulation of VEGFA." (PMID 30755242, 2019). "Taken together, we have determined that IFN-I regulates CTL effector function through activating the STAT3-granzyme B axis in anti-tumor immune response." (PMID 31228946, 2019). "Next, we checked the effect of miR-410-3p on STAT3, a critical regulator of malignant transformation and tumor progression." (PMID 31165412, 2019). "In vivo experiments on mice with CRC xenografts reflected similar results with doses of 2 mg/kg and 4 mg/kg reducing p-STAT3 32% and 80%, and tumor volume 35% and 58% respectively." (PMID 31671769, 2019). "On the other hand, SHP1 has been found to act as a tumor suppressor in liver cancer by deactivating STAT3 and subsequent errant NFκB signaling." (PMID 31842362, 2019). "We will describe how STAT3 affects both myeloid and lymphoid cells usually in a way to inhibit anti-tumor immune response and to promote tumor growth." (PMID 31480382, 2019).
tumor (continued). "APN inhibits STAT3 activation that increases tumor cell proliferation, survival, angiogenesis and invasion, as well as inhibiting anti-tumor immunity." (PMID 30781341, 2019). "This family exerts its activity by stimulating the cellular components in the tumour microenvironment and in cancer stem-like cells, which regulate pathways that promote EMT of tumour cells, propelling them to migrate via the STAT3 pathway." (PMID 31196220, 2019). "Further, it has been reported that STAT-3 is activated in most human HCCs and presents positive correlation with tumor malignancy." (PMID 31456946, 2019). "The oncogenic transcription factor STAT3 represents a key signaling hub regulating many tumor-related processes including proliferation, migration, apoptosis-resistance, angiogenesis and immune evasion." (PMID 30857197, 2019). "IL-6 mediates STAT3 activation in tumor and tumor progression, and IL-6 neutralization reduces STAT3 activity in vivo." (PMID 31533774, 2019). "This study demonstrates that CDK5 promotes GBM tumor growth through TRIM59-mediated STAT3 signaling activation." (PMID 31488827, 2019). "We identified four STAT3 groups (T-STAT3-high/E-STAT3-high, T-STAT3-high/E-STAT3-low, T-STAT3-low/E-STAT3-high, and T-STAT3low/E-STAT3-low) with distinct tumor characteristics." (PMID 31796877, 2019). "Constitutively active STAT3 induces deregulation of growth and survival, promotion of angiogenesis, and suppression of host's immune surveillance against tumor." (PMID 31781335, 2019). "Our study thus explains the role of IL-6 autocrine signalling in activating the STAT3 pathway in ADSCs and the effects of blocking IL-6 on the tumour-promoting activity of activated epidural ADSCs." (PMID 31196220, 2019). "The high expression of STAT3 has been correlated to large tumor diameter and depth, lymph node metastasis, high expression of MMP-2 and -9, and poor patient survival." (PMID 30691132, 2019). "Recent studies underscore the involvement of STAT3 in PC through its regulation of tumor cell proliferation, survival, tumor invasion and angiogenesis." (PMID 30674340, 2019). "Tumor-associated macrophages (TAM) release IL6, which activates the IL-6 receptor (IL6R)/STAT3 pathway in CRC cells." (PMID 31885581, 2019). "Several studies reported constitutive STAT3 phosphorylation of tumor-infiltrating immune cells including NK cells." (PMID 31781102, 2019). "A series of cytokines and chemokines can activate STAT3 in tumor cells, among which IL-6 and IL-1β are the major inducers derived from the TME." (PMID 30927928, 2019). "JAK2/STAT3 signaling played an essential role in promoting tumor initiation and radioresistance by limiting apoptosis and enhancing clonogenic potential." (PMID 31511084, 2019). "The present study has proved that dovitinib induced a significant tumor-inhibitory effect through blockade of p-STAT3 via SHP-1 activation." (PMID 31485222, 2019). "IFN-I induces STAT3 activation to activate Gzmb expression to enhance CTL effector function to suppress tumor development." (PMID 31228946, 2019). "Small-molecule inhibitors or siRNA for targeting STAT3 signaling have also met with success in mice tumor models." (PMID 31775797, 2019). "STAT3 inhibits the tumor suppressor miR-204-5p, leading to chemoresistance to 5-FU and to oxaliplatin." (PMID 31885581, 2019). "In humans, tumor-derived factors suppress DC generation through STAT3-mediated PKCβII reduced expression." (PMID 31480382, 2019). "It is likely that the combination of high E- and T-STAT3 activities confers tumor growth advantages compared to other STAT3 groups." (PMID 31796877, 2019). "Overexpression of STAT3 has been shown plays a role in maintaining tumor progression and low survival rate in various malignancies." (PMID 31287013, 2019). "In similar studies, the tumor suppressor functions of STAT3 were found to have relevance with Ras and p19ARF protein expression." (PMID 31847229, 2019).